PDCD4 (programmed cell death 4)
Diseases named in the same sentence as PDCD4 in open-access papers (continued):
Sharing a sentence is not in itself a finding about the gene and the disease.
tumor (continued). "In addition, PDCD4 is a newly found molecule that plays a vital role on many biological processes that may cause disease or occurrence and development of tumor." (PMID 25144746, 2014). "Specifically, miRNA-34a suppresses expression of CD24 and Src, thereby diminishing the tumor progression-associated functions of these genes, which results in reduced expression of the oncomir miR-21, and thus relieves miR21-mediated repression of Pdcd4 and PTEN expression." (PMID 23533633, 2013). "Overall, the information obtained in untransformed cells provides a new perspective for the role of PDCD4 as a tumour suppressor." (PMID 41626692, 2026). "Functionally, Pdcd4-Rictor interaction suppressed glycolytic activity and inhibited tumor cell proliferation in cultured cells and xenograft models." (PMID 42078886, 2026). "Although Pdcd4-mediated translational repression contributes to tumor suppression, emerging evidence suggests that Pdcd4 also exerts translation-independent functions." (PMID 42078886, 2026). "Programmed cell death 4 (Pdcd4) is a well-established tumor suppressor and inhibitor of protein translation." (PMID 42078886, 2026). "Mechanistically, miR-183 directly represses PDCD4, a proapoptotic gene, contributing to tumor progression." (PMID 41596525, 2026). "Programmed cell death 4 (PDCD4) is a tumor suppressor with reduced expression in several cancers, and PDCD4 overexpression inhibits tumorigenic." (PMID 40275278, 2025). "PDCD4 is a tumor suppressor with reduced expression in several cancers and PDCD4 overexpression can inhibit tumorigenic." (PMID 40275278, 2025). "We found that the tumor suppressor genes Pten and Pdcd4, downstream targets of mmu-miR-21a-5p, were upregulated in CT-2A tumor-bearing mice when mmu-miR-21a was knocked out in AAV8-CRISPR-treated mice." (PMID 39563028, 2025). "A natural product, erioflorin, inhibits the interaction between the tumor-suppressive PDCD4 protein and β-TrCP1." (PMID 40646550, 2025). "Mechanistically, PDCD4 suppresses the production of tumor‐derived M2‐polarizing factors by binding to eIF4A, whereas its loss induces eIF4A‐dependent overtranslation of immunosuppressive proteins." (PMID 40908584, 2025). "Programmed cell death 4 (PDCD4) serves as a tumor suppressor in NSCLC that enhances the sensitivity of NSCLC cells to DDP." (PMID 40296912, 2025). "As a novel tumor suppressor, PDCD4 interacts with eukaryotic translation initiation factor 4 A (eIF4A), crucially functioning as a translational repressor." (PMID 39885142, 2025). "Programmed Cell Death 4 (PDCD4), initially identified as a neoplastic transformation inhibitor, has emerged as an important tumor suppressor gene across multiple cancer types." (PMID 41614853, 2025). "Here, the overexpression of PDCD4 was shown to significantly induce apoptosis in A549 and H23 cells, confirming the tumor-suppressive role of PDCD4." (PMID 39885142, 2025). "Some in vitro HNSCC cell line work suggests that inhibiting miR-21 can sensitize tumor cells to cisplatin or radiotherapy by upregulating PDCD4 and PTEN." (PMID 41226828, 2025). "Although the role of PDCD4-mediated translation inhibition has been extensively studied in tumor development, its nuclear function remains poorly understood." (PMID 41234771, 2025). "Studies have demonstrated that overexpression of PDCD4 leads to cell cycle arrest by upregulating inhibitors such as p21 and p27, eventually suppressing tumor growth." (PMID 39891297, 2025). "In vivo, PDCD4 overexpression in BPC cells led to a significant reduction in subcutaneous tumor volume." (PMID 40908584, 2025). "The findings that Slug knockdown partially reverses the effects of Pdcd4 knockdown in elevating E‐cadherin expression and repressing invasion suggest that Slug contributes to Pdcd4 knockdown‐mediated tumor invasion." (PMID 40785580, 2025).
tumor (continued). "Its differential expression promotes tumor cell proliferation and metastasis by targeting tumor suppressors such as PDCD4 and PTEN and regulating inflammatory pathways, including NF-κB." (PMID 40869212, 2025). "Other PCa oncogenic events, such as loss of Pdcd4 or activation of the MNK/eIF4E pathways, have been described to impact cell secretome protein composition affecting and promoting immune evasion and tumor progression." (PMID 40268923, 2025). "Our results imply a more complex function for PDCD4 across various malignancies, challenging its long-standing reputation as a tumor suppressor." (PMID 40766329, 2025). "And EVs secreted by chemotherapy-resistant cells transport miR-21-5p (known to target tumor suppressors such as PDCD4) or PVT1, further inhibiting T cell activity." (PMID 40924501, 2025). "Downregulation of PDCD4 by miR-21 contributes to enhanced tumor cell migration, invasion, and metastasis." (PMID 41240165, 2025). "The miR-21-5p directly targets PDCD4, a tumor suppressor involved in apoptosis and inhibition of invasion." (PMID 41240165, 2025). "Programmed cell death protein 4 (PDCD4) is a tumor suppressor that activates NF-κB and inhibits IL-10 expression." (PMID 39910395, 2025). "PDCD4 is a novel tumor suppressor with multiple functions that modulate transcription and translation." (PMID 41439995, 2025). "Programmed cell death 4 (Pdcd4), a tumor suppressor, is known to inhibit translation via interaction with eukaryotic initiation factor 4A (eIF4A)." (PMID 40785580, 2025). "The role of PDCD4 in the translation of several tumor-suppressive genes involved in cancer cell proliferation, invasion, and metastasis is well-established." (PMID 39885142, 2025). "Programmed cell death factor 4 (PDCD4) is a tumor suppressor gene, which can inhibit cell growth, tumor invasion and metastasis, and it induces cell apoptosis." (PMID 40843171, 2025). "In RCC specifically, previous studies have suggested that PDCD4 downregulation correlates with tumor progression and metastasis, consistent with our observation that signature scores decrease progressively with advancing tumor stage." (PMID 41614853, 2025). "PDCD4, a tumor suppressor that is downregulated in many cancers, is also suppressed by serum, EGF, or TPA treatment." (PMID 41439995, 2025). "The stabilization of PDCD4 results in the reduced expression of key genes involved in tumor cell proliferation and invasion." (PMID 41034525, 2025). "PDCD4’s dual roles in both tumor suppression and metabolic regulation position it as a potential integrative biomarker that captures both proliferative and metabolic aspects of RCC biology." (PMID 41614853, 2025). "Overexpression of DTL, for instance, can decrease PDCD4 expression levels, promote intracellular PDCD4 ubiquitination, accelerate tumor cell growth, and enhance invasive capabilities." (PMID 39367897, 2025). "PDCD4 functions as a tumor-suppressor gene through regulation of cell growth, apoptosis, tumor invasion, and metastasis." (PMID 41234771, 2025). "PDCD4 is a suppressor of tumor progression that leads to cell cycle arrest, increased apoptosis, and increased sensitivity of tumor cells to drugs." (PMID 40004462, 2025). "Conversely, tumor-suppressive circRNAs like circMKLN1 enhance anti-tumor immunity by upregulating PDCD4, a key regulator of antigen processing and presentation, thereby facilitating CD8+ T cell activation." (PMID 41041300, 2025). "Originally identified as a gene upregulated during apoptosis, PDCD4 functions as a translational repressor by binding to eukaryotic translation initiation factors, thereby inhibiting protein synthesis required for tumor progression." (PMID 41614853, 2025). "Blocking miR-21 restored tumor suppressors such as PTEN and programmed cell death 4 (PDCD4), reduced tumor growth, and enhanced doxorubicin sensitivity." (PMID 40943288, 2025).
tumor (continued). "PDCD4 functions as a tumor suppressor and an inhibitor of protein translation and participates in apoptosis regulation." (PMID 41462911, 2025). "Programmed cell-death protein 4 (PDCD4) functions as a tumor suppressor by inhibiting the c-Jun pathway, which is associated with cancer cell proliferation and invasion." (PMID 41034525, 2025). "To date, erioflorin activity has been mainly attributed to its ability to stabilize the tumor suppressor protein Pdcd4, a tumor suppressor that inhibits protein translation and activation of the mTORC2-Akt axis, which induces apoptosis and arrests cell growth." (PMID 40126263, 2025). "PDCD4 is a newly identified tumor suppressor that induces apoptosis and suppresses cell proliferation, invasion, and metastasis." (PMID 40766329, 2025). "These functional connections suggest that the PDCD4 signature reflects coordinated dysregulation of multiple tumor-suppressive pathways in RCC." (PMID 41614853, 2025). "The miR-21-mediated downregulation of PDCD4 can lead to enhanced tumor cell growth and decreased apoptosis." (PMID 39100039, 2024). "The downregulation of PDCD4 by miR-21 contributes to enhanced cell proliferation and resistance to apoptosis, further facilitating tumor progression." (PMID 39452836, 2024). "Bioinformatics analyses have revealed that PDCD4 acts as a tumor suppressor by regulating processes like cell proliferation, invasion, metastasis, and tumor transformation through its interaction with miR-21." (PMID 39114567, 2024). "miR-21 specifically targets PTEN and PDCD4 through the PI3K/AKT/mTOR pathway to promote tumor growth." (PMID 39857631, 2024). "And it has been demonstrated that the inhibition of lysosome function by PDCD4 depends on TFEB, and in the TME, PDCD4 deficiency can promote the anti-tumor effect of macrophages by enhancing TFEB expression." (PMID 38370407, 2024). "Programmed cell death 4 (PDCD4) functions as a tumour suppressor and an inhibitor of protein translation." (PMID 38540190, 2024). "PDCD4 (programmed cell death protein 4), a known tumor suppressor, was further found to have prognostic value in clinical PCa samples." (PMID 39147845, 2024). "miR-21 expression is associated with tumor growth and metastasis, by suppressing tropomyosin alpha-1 (TPM1) and programmed cell death 4 (PDCD4), affecting the mammalian target of rapamycin (mTOR) pathway." (PMID 39335585, 2024). "Pdcd4 was initially recognized as a tumor suppressor because its downregulation in promotion-resistant mouse epidermal JB6 cells led to the acquisition of a promotion-sensitive phenotype." (PMID 39459035, 2024). "Of these targets, we select ARHGAP17, FOXO3A, and PDCD4 as known tumour suppressors in cancer and experimentally validate the interaction of miR-4787-3p with their 3’UTRs." (PMID 39003349, 2024). "Beyond its role in tumor suppression, growing evidence suggests that Pdcd4 enhances the chemosensitivity of several anticancer drugs." (PMID 39459035, 2024). "Third, the Arg residue at position 110 can be methylated by protein arginine methyltransferase 5 (PRMT5) and this methylation impairs the Pdcd4’s tumor suppressor function." (PMID 39459035, 2024). "notably, PDCD4 sensitizes cancer cells to cisplatin, paclitaxel, and doxorubicin by acting as a tumor suppressor to induce apoptosis." (PMID 39830506, 2024). "Subsequently, Pdcd4 was found to exert multifaceted effects, including inhibiting tumor cell invasion and metastasis, reducing proliferation, suppressing inflammation, and promoting apoptosis." (PMID 39459035, 2024). "Programmed cell death 4 (Pdcd4) is a tumor suppressor and a protein translation inhibitor, which has been shown to efficiently inhibit cell proliferation, survival, migration, and invasion in various cancer cells." (PMID 39459035, 2024). "Pdcd4 is a tumor suppressor protein known to suppress cell growth, tumor invasion, and metastasis, and is downregulated in nearly all solid tumors." (PMID 39117603, 2024).
tumor (continued). "Tumor suppressor protein Pdcd4 is downregulated in tumor cells, whereas global mRNA translation within these cells is upregulated." (PMID 39117603, 2024). "Programmed cell death 4 (PDCD4) is a tumor suppressor gene that suppresses tumor migration, invasion, EMT and angiogenesis." (PMID 39030557, 2024). "Programmed cell death 4 (Pdcd4) is a tumor suppressor, which has been demonstrated to efficiently suppress tumorigenesis." (PMID 39459035, 2024). "Expression of the tumor suppressor PDCD4, which was downregulated in untreated AD, was restored in DAHND lesions." (PMID 38565563, 2024). "The tumor suppressor function of PDCD4 is repressed by miR-21 at a post-transcriptional level, leading to increased proliferation, invasion, and metastasis in RCC." (PMID 39114567, 2024). "PDCD4, another miR-21 target, is involved in the regulation of transcription and translation and acts as a tumor suppressor by inhibiting neoplastic transformation and invasion." (PMID 39100039, 2024). "Erioflorin interferes with the interaction of β-TrCP with programmed cell death 4 (Pdcd4), a tumor suppressor, resulting in stabilization of Pdcd4, reducing AP-1- and NF-κB-dependent transcription that alters the cell cycle and inhibits proliferation in vitro." (PMID 37176148, 2023). "Programmed cell death (PDCD4), known as a tumor suppressor, has functions, such as modulating signaling pathways, diminishing tumorigenesis, and influencing the translation and transcription process of multiple genes." (PMID 37438760, 2023). "These miRNAs promote cell proliferation and metastasis, and they can target tumor suppressor genes like PTEN and PDCD4, leading to their downregulation and loss of their tumor-suppressing functions." (PMID 37631277, 2023). "Inhibition of miR-21 in MPNST cell lines showed suppressed cell growth and upregulated levels of its target protein, programmed cell death protein 4 (PDCD4), which is known to act as a tumour suppressor gene and is upregulated during apoptosis." (PMID 36765536, 2023). "The tumour suppressive substrates include inhibitor of nuclear factor kappa B (IκB), programmed cell death protein 4 (PDCD4) and forkhead box protein O3 (FOXO3)." (PMID 37293994, 2023). "Among them, PDCD4 is an important tumour suppressor that inhibits carcinogenesis, tumour progression and invasion by inhibiting translation." (PMID 37461031, 2023). "The outcomes also involved a rise in the expression of Phosphatase and tensin homolog (PTEN) and Programmed cell death 4 (Pdcd4) proteins and a reduction in tumor size." (PMID 38304326, 2023). "PDCD4 is a tumor suppressor protein that inhibits translation by binding to translation initiator eIF4A, thereby promoting apoptosis and inhibiting tumor cell proliferation and invasion." (PMID 37308277, 2023). "the silencing of HNRNPC inhibited proliferation and invasion, decreasing the expression of mi-R-21 and thus increasing the expression of its target programmed cell death 4 (PDCD4), a protein associated with tumour suppression." (PMID 37444417, 2023). "In murine tumor models, miR-21a found within TDEs has the remarkable capacity to significantly promote the expansion and suppressive function of MDSCs by targeting Programmed Cell Death Protein 4 (PDCD4)." (PMID 38087360, 2023). "A reduction in PDCD4 expression is observed in advanced breast and prostate carcinomas hence it is considered to be a tumour suppressor." (PMID 37293994, 2023). "It is noteworthy that 98 and 105 were the first reported marine natural products to stabilise PDCD4 under tumour-promoting conditions." (PMID 36771114, 2023). "PDCD4 acts as a protein translation inhibitor, and thus inhibits tumor cell proliferation, migration and invasion." (PMID 38081915, 2023). "The programmed cell death protein 4 (PDCD4), a well-known tumor suppressor, inhibits translation initiation and cap-dependent translation by inhibiting the helicase activity of EIF4A." (PMID 36826085, 2023).
tumor (continued). "PDCD4, a gene involved in tumor suppression by inhibiting the helicase activity of eIF4A and protein translation, is a direct target for miR-182 and is downregulated by overexpression of miR-182." (PMID 37438760, 2023). "It is well documented that PDCD4, a tumor suppressor, can suppress tumor proliferation and progression and is often down-regulated in many types of human cancer." (PMID 36826085, 2023). "PDCD4 is another novel tumor suppressor with multi-functions inhibiting tumor cell proliferation, tumor invasion and metastasis." (PMID 36366842, 2023). "In previous studies, anti‐miR‐21 oligonucleotide (AMO21) delivery was shown to decrease miR‐21 levels and consequently the expression of PTEN and PDCD4 in tumor tissue." (PMID 36925699, 2023). "For instance, miR-21 is an oncogenic miRNA that targets tumor suppressor genes such as PTEN and PDCD4, while miR-34a is a tumor suppressor miRNA that targets oncogenes such as MYC and BCL2." (PMID 37460924, 2023). "The PDCD4 gene is involved in important processes in cell regulation, considering that it is a tumor suppressor." (PMID 37047756, 2023). "During the current study, we intended to search the potential SUMOylation sites on PDCD4 since SUMOylation is one of the PTMs frequently found on tumor suppressors." (PMID 36826085, 2023). "It reduces the expression of several tumor-suppressor genes, including programmed cell death 4 (PDCD4) and reversion-inducing cysteine-rich protein with Kazal motifs (RECK)." (PMID 37627167, 2023). "The PDCD-4 gene is part of a class of tumour suppressors, which is located in the nucleus and can inhibit cell proliferation and promote apoptosis through the Sp transcription factor." (PMID 38041032, 2023). "The compound inhibited the interaction between the tumour suppressive PDCD4 protein and βTrCP, although the mechanism by which this occurs has not been fully elucidated." (PMID 37293994, 2023). "These anti-tumor and anti-metastatic effects were connected with decreased levels of pAkt, miR-21, and greater levels of PDCD4." (PMID 37843642, 2023). "Programmed cell death 4 (PDCD4), one of the major tumor suppressors involved in the cell death mechanism, has an inverse correlation with oncogene miR-182." (PMID 36778005, 2023). "PDCD4 has been labelled a tumour suppressor in part due to the inverse relationship between expression and cell proliferation." (PMID 35847932, 2022). "Circ-ITCH specifically targets miR-106b-5p and miR-421 in clear cell renal cell carcinoma (ccRCC) and oral squamous cell carcinoma (OSCC) to up-regulate PDCD4 expression and prevent tumor progression, respectively." (PMID 35910224, 2022). "CC cells can produce exosomal miR-208b to receptor T-cells and promote the expansion of Treg cells via programmed cell death factor 4 (PDCD4), leading to malignant tumor growth and oxaliplatin resistance." (PMID 36211364, 2022). "PDCD4 is a known tumour suppressor which can inhibit translation in the cytoplasm and affect gene transcription in the nucleus, potentially thereby modulating proliferation, differentiation and apoptosis." (PMID 35847932, 2022). "A classic example is that miR-182 and miR-183 facilitate cell proliferation and tumor invasion by inhibiting PDCD4 in various cancer cells, which is a typical tumor suppressor gene." (PMID 36290185, 2022). "PDCD4 has been demonstrated to be a protein translation inhibitor and a tumor suppressor, and consistently its expression frequently decreased in numerous types of malignancies including breast, colon, liver, lung, pancreatic, and skin cancers." (PMID 35795053, 2022). "PDCD4 is a new tumor suppressor that exhibits a wide range of actions, including the inhibition of cell proliferation, tumor invasion, metastasis, and the induction of apoptosis." (PMID 35865469, 2022).